TMPO-AS1 (TMPO antisense RNA 1)
Gene: Long non-coding RNA gene on chromosome 12 (98,512,791 to 98,516,422, reverse strand). Ensembl gene ENSG00000257167.
Diseases named in the same sentence as TMPO-AS1 in open-access papers:
TMPO-AS1 is named in the same sentence as 15 diseases in open-access papers, as found by Europe PMC text mining. Sharing a sentence is not in itself a finding about the gene and the disease. The quoted sentences say what the papers report.
breast carcinoma (2 papers, 2021 to 2025). "Recent reports have implicated TMPO-AS1 in various oncogenic processes in breast cancer." (PMID 41268575, 2025). "Recent studies have demonstrated that TMPO antisense RNA 1 (TMPO-AS1) serves as a competing endogenous RNA to sponge microRNAs (miRNAs) in multiple carcinomas, including hepatocellular carcinoma, thyroid cancer, lung adenocarcinoma, and breast cancer." (PMID 33816295, 2021).
colorectal cancer (2 papers, 2020 to 2024). A primary or metastatic malignant neoplasm that affects the colon or rectum. "Furthermore, TMPO‐AS1 is also identified as an underlying therapeutic target for patients diagnosed with cancers, including colorectal cancer, prostate cancer, and lung adenocarcinoma." (PMID 32462698, 2020). "All the results clarified that TMPO-AS1 knockdown restrained the malignant characteristics of colorectal tumor cells, supposing that TMPO-AS1 had oncogenic effects in colorectal cancer." (PMID 38383342, 2024).
lung adenocarcinoma (2 papers, 2020 to 2021). A carcinoma that arises from the lung and is characterized by the presence of malignant glandular epithelial cells. "More importantly, aberrant expression of lnc RNA TMPO antisense RNA 1 (TMPO‐AS1) promotes lung adenocarcinoma, prostate cancer." (PMID 32462698, 2020).
ovarian carcinoma (2 papers, 2021 to 2023). A malignant neoplasm originating from the surface ovarian epithelium. "For instance, TMPO-AS1 is overexpressed in ovarian cancer and promotes cancer progression via increasing LCN2 transcription." (PMID 34330309, 2021). "Moreover, TMPO-AS1 has the potential to enhance LCN2 transcriptional activity by binding to transcription factor E2F6, thus stimulating ovarian cancer progression." (PMID 37592311, 2023).
bladder cancer (1 paper, 2021). "It has been reported that lncRNA TMPO antisense RNA 1 (TMPO-AS1) expression is upregulated in bladder cancer tissues and cells, where it promotes cell growth, migration and invasion." (PMID 34036383, 2021).
colorectal tumor (1 paper, 2024). "We further assessed TMPO-AS1 abundance in colorectal tumor tissues from clinical surgery." (PMID 38383342, 2024).
osteosarcoma (1 paper, 2020). A usually aggressive malignant bone-forming mesenchymal neoplasm, predominantly affecting adolescents and young adults. "Recently, TMPO-AS1 has been identified as a competitive endogenous RNA that promotes tumorigenesis of osteosarcoma by regulating the miR-199a-5p/WNT7B axis, which provides a potential therapeutic target for osteosarcoma patients." (PMID 33117415, 2020).
cancer (7 papers, 2020 to 2024). A tumor composed of atypical neoplastic, often pleomorphic cells that invade other tissues. "Long noncoding RNA thymopoietin-antisense RNA 1 (TMPO-AS1) is recognized as a participant in cancer progression." (PMID 38383342, 2024). "Recently, thymopoietin-antisense RNA 1 (TMPO-AS1), functioning as a novel regulator to play roles in cancer, has drawn much attention." (PMID 38383342, 2024). "Analysis of TCGA data showed upregulated TMPO-AS1 expression in tumor samples compared to normal tissues in various types of cancer tissues, especially in ESCA tissues." (PMID 35760875, 2022). "As a matter of fact, mounting evidence has demonstrated that TMPOAS1 plays an oncogenic role in the progression of cancer." (PMID 35311097, 2022). "TMPO antisense RNA 1 (TMPO-AS1) has been found to be involved in several cancers by acting as a competing endogenous RNA." (PMID 33816295, 2021). "Actually, TMPO-AS1 has been identified as an oncogene in various carcinomas." (PMID 37542040, 2023). "According to the result that TMPO‐AS1 mainly distributed in cytoplasm, confirmed by subcellular fractionation assay.We speculated that TMPO‐AS1 possibly affects cancer progression via ceRNA regulation pattern." (PMID 32462698, 2020). "Furthermore, TMPO-AS1 knockdown restrained proliferation, decreased the migrative and invasive abilities, and accelerated apoptosis in SW480 cells, following the previous reports of TMPO-AS1's oncogenic effect on other types of cancer cells." (PMID 38383342, 2024).
TMPO-AS1 also shares sentences with these, for which no sentence is quoted: tumor (2 papers); cholangiocarcinoma (1); esophageal cancer (1); hepatocellular carcinoma (1); laryngeal squamous cell carcinoma (1); prostate carcinoma (1); thyroid cancer (1).